TERT (telomerase reverse transcriptase)
Diseases named in the same sentence as TERT in open-access papers (continued):
Sharing a sentence is not in itself a finding about the gene and the disease.
tumor (continued). "Hence, the high frequency of these variants in PSCC provides opportunities for the development of anticancer strategies and applications of TERT as a potential biomarker for the diagnosis and prognosis of neoplasms." (PMID 35884575, 2022). "While in these 7 tumor samples, TERT expression was only detected in one dog (GLP25; DogWUR113)." (PMID 36151521, 2022). "TERT mRNA levels were higher in urine from patient tumors bearing TERT promoter mutations, while not related to tumor size, grade and stage." (PMID 36713366, 2022). "Previous reports have demonstrated that apoptosis is inhibited by mutant TERT in tumor cells." (PMID 35053139, 2022). "When overexpressing telomerase reverse transcriptase (telomerase catalytic subunit; TERT) in mouse models for either anti-tumor therapy or advanced age, their median survival time increased independently from the tumor incidence, indicating that telomere length contributes to survival during aging." (PMID 35000109, 2022). "However two out of nine widely invasive‐FTC tumours were identified to harbour TERT gene fusion or rearrangement, and both expressed dramatically high levels of TERT mRNA." (PMID 36394204, 2022). "Bases editing by CRISPR/Cas9 could correct TERT mutation and reduce the binding activity of ETS transcription factors to slow down tumor growth, but the prospect of gene therapy in clinic is still open to question." (PMID 35135556, 2022). "However, ERV and IFN signal stimulate the infiltration of suppressor T cells at the same time, indicating that IFN signal mediated by TERT accounts for tumor immunosuppression." (PMID 36119095, 2022). "TERT was detected in 6 tumor (86%) and 4 (57%) adjacent tissue." (PMID 33530592, 2021). "The average number of breakpoints in tumor samples with and without TERT mutations was 7.6 and 12.8, respectively." (PMID 34209079, 2021). "Moreover, patients that were ctDNA+ (or TERT C228T+) or with CTC ≥ 2 had significantly worse tumor-specific survival." (PMID 33915518, 2021). "Human telomerase (TERT) is reactivated in approximately 90% of all cancers, while in approximately 10% of tumours, telomere length is maintained, independently of TERT, by the homologous recombination‐mediated alternative lengthening of the telomere (ALT) pathway." (PMID 33713376, 2021). "Circulating anti-tumor Th1 response was assessed by the ELISpot assay using a mixture of human leucocyte antigen (HLA) class II restricted peptides derived from telomerase (TERT)." (PMID 34144673, 2021). "Univariable regression analysis identified tumor grade, TERT promoter mutations, patient age, and tumor size as independent negative prognostic variables." (PMID 34108637, 2021). "We next examined whether the different components of the cluster are also involved in TERT‐mediated tumour invasion." (PMID 33713376, 2021). "Although all recurrent PTCs with transformation acquired TERT promoter mutation at the time of the primary tumor, we found TERT promoter mutation in 4 recurrent PTCs without transformation only in lymph node metastases." (PMID 33761111, 2021). "Also TERT C228T VAF significantly correlated with largest tumor diameter (r = 0.41, P = 0.037) and AFP (Log10) level (r = 0.55, P = 0.004)." (PMID 33915518, 2021). "By determining the chromosomal instability index, it was found that the tumor chromosomal instability index of the TERT promoter mutation was significantly higher than that of the tumor without the TERT promoter mutation." (PMID 34094968, 2021). "After adjustment for age, the association of TERT mRNA levels above the cut-off with the risk of tumor development was still high, but not significant (HR=2.5, 95%C.I." (PMID 34746013, 2021). "Whether the net effects of TERT are pro- or anti-tumor depends on the stage of disease, tissue type, telomere biology in different animal models, when during tumor formation TERT is manipulated, and other factors." (PMID 34439356, 2021).
tumor (continued). "However, further research investigating the associations of IRF4 rs12203592, CCND1 rs1485993, TERT rs2242652, and MX2 rs45430 with underlying biologic pathways related to tumor progression is warranted." (PMID 34898573, 2021). "Furthermore, we found that TERT mutation status (p = 0.003), as well as extent of resection (EOR) (p < 0.001), was significantly associated with tumor progression by Fisher’s exact tests." (PMID 34778063, 2021). "Therefore, one would predict that loss-of-function mutations in TERT or TERC would inhibit tumorigenesis, while overexpression of TERT would promote tumor formation." (PMID 34439356, 2021). "Moreover, TERT mRNA expression was scattered across the tissue sections and only found in a few percentages of tumour nuclei." (PMID 34011619, 2021). "The mechanism by which TERT promoter mutation potentiates tumor development is not fully understood." (PMID 33761111, 2021). "Chromosome 1q and TERT amplifications are correlated with aggressive tumour biology." (PMID 34062862, 2021). "In addition, beyond immortalization, TERT also possess telomere independent functions in tumor formation, regulating Wnt-dependent transcription, mitochondrial function, apoptosis, and DNA damage response." (PMID 34048184, 2021). "Amplification of Telomerase reverse transcriptase (TERT) and loss of cyclin dependent kinase inhibitor 2A/2B (CDKN2A/CDKN2B) detected in the tumor by next gene sequencing suggests that they may play an important role in this case." (PMID 34127009, 2021). "Furthermore, TERT alterations (TERT-alt) were the predictor of tumor progression (Fisher’s exact tests, p = 0.003) and were associated with decreased PFS (log-rank test, p = 0.0114) in de novo HGMs after RT." (PMID 34778063, 2021). "The tumorigenesis of MirCs was also denied by measuring the expression of TERT as a tumor marker." (PMID 34035362, 2021). "Moreover we showed that ctDNA positivity was associated with overall and tumor-specific survival in our HCC patients and TERT C228T mutation alone is a significant predictor of survival." (PMID 33915518, 2021). "Telomerase (TERT) function is usually high in gamete, stem, and tumor cells." (PMID 34679783, 2021). "The metastasis-free survival (MFS) of patients with a TERT promoter mutation was significantly shorter as compared to patients without a TERT promoter mutation in the tumor (p = 0.008)." (PMID 34071371, 2021). "In silico analysis predicted the A allele of SNP rs2075786 eliminates a retinoid binding site, causing natural retinoids not to efficiently limit TERT expression, culminating in accelerated tumour growth." (PMID 34059744, 2021). "However, TERT-positive cases only exhibited nuclear signals in small subsets of tumour cells, thereby forcing the pathologist to scrutinise the whole slide using high power (×400 or ×1000) magnification." (PMID 34011619, 2021). "Although MYC and E2F1 are two well-studied oncogenic transcription factors that are frequently dysregulated in PCa cells, whether the two genes together with TERT have synergistic effects on tumor severity are still unclear." (PMID 34858826, 2021). "Moreover, we found that Costunolide, a TERT inhibitor, was effective in reducing the cell viability in vitro of both primary tumor models as well as tumor models pre-treated with chemotherapy and radiotherapy." (PMID 33919246, 2021). "Expression of TERT, which is usually repressed in normal somatic cells, is essential to sustain the unlimited replicative potential of cancer cells showing a critical role in tumor formation and progression." (PMID 34746013, 2021). "Telomere length was correlated with TERT alterations and tumor characteristics." (PMID 33946181, 2021). "Conversely, telomere length in tumour tissue did not significantly differ according to the mutational status of TERT promoter (p=0.1182)." (PMID 34858860, 2021).
tumor (continued). "TERT gene aberrancies are common in various cancers and usually confer an increased TERT mRNA gene output, which is thought to confer immortalization through the elongation of telomeric DNA for these tumor types." (PMID 33768452, 2021). "In addition to heterogeneity in TERT expression patterns across and within tumor types, cancer cell lines are also reported to exhibit TERT isoform expression heterogeneity." (PMID 33924498, 2021). "In the univariate analysis of DTC patients, age (p < 0.001), TERT mutation status (p < 0.001), histological type (p = 0.004), ETE (p < 0.001), distant metastasis (p < 0.001), stage at diagnosis (p < 0.001), and tumor size (p = 0.014) were significant predictors." (PMID 33562809, 2021). "The absence of TERT promoter mutations in NB tumor samples allows us to exclude this mechanism as the main one responsible for TERT overexpression in NB." (PMID 34072462, 2021). "By synthesizing the telomere sequences and thus preventing cell senescence and apoptosis, the inappropriate activation of the catalytic component of the telomerase, telomerase reverse transcriptase (TERT), appears crucial for maintaining cellular replicative capacity and allowing tumour formation." (PMID 34858860, 2021). "The tumor biology is associated with the status of different molecular markers, such as isocitrate dehydrogenase (IDH), 1p/19q codeletion, and telomerase reverse transcriptase (TERT) mutation." (PMID 33613747, 2021). "In addition to TERT promoter mutations, CM frequently harbors BRAF mutations, which are known to activate the downstream kinases MEK1/2 and ERK1/2, resulting in tumor proliferation." (PMID 34071371, 2021). "Taken together, these results show that miR500A mediates TERT‐driven tumour invasiveness." (PMID 33713376, 2021). "These tumours also showed a high expression of the TERT (Telomerase Reverse Transcriptase) gene." (PMID 33530592, 2021). "Therefore, to reveal the regulatory mechanisms of the transcription of TERT gene is important for understanding the tumor development." (PMID 34489496, 2021). "Unmethylated THOR suppressed TERT promoter activity regardless of TERT promoter mutations while hypermethylation of this region increased promoter activity in human tumours." (PMID 33802026, 2021). "A limitation of evaluating TERT expression by ddPCR is that lymphocytes are also known to express TERT, and therefore lymphocyte contamination of the tumor sample could theoretically produce a false positive result." (PMID 34702207, 2021). "Therefore, we used an inducible TERT-KD construct, allowing for treatment to commence after tumor formation and growth, replicating the therapeutic scenario in a clinical setting without the confounding off-target effects of small molecule inhibitors." (PMID 34201898, 2021). "Hence, we reasoned that the addition of TERT DNA immunogen would not only target the prototype vaccine to tumor cells, but would also further enhance the immune response against HCV core." (PMID 34067686, 2021). "Telomerase reverse transcriptase (TERT) is a subunit component of telomerase with reverse transcriptase activity and participates in maintaining telomere ends and chromosomal stability, which is a critical member in tumor suppressive mechanism." (PMID 34900720, 2021). "PIF1 acts as a tumor promoter in CC via suppressing the TERT." (PMID 34181336, 2021).
tumor (continued). "These novel roles of TERT may endow transformed cells with specific capacities in many stages of tumour development." (PMID 33713376, 2021). "Amplification of TERT and loss of CDKN2A/CDKN2B detected in the tumor by next gene sequencing suggests that they may play an important role in this case." (PMID 34127009, 2021). "TERT promoter mutations occur exclusively in tumor cells and not in normal somatic cells or stem cells." (PMID 33397920, 2021). "In addition, stimulated by the recently reported predictive and prognostic relevance of blood TERT mRNA levels in various clinical settings, we also investigated the circulating TERT mRNA levels as early marker of tumor development in SOT recipients." (PMID 34746013, 2021). "Comparing our findings with mutational profiles of other tumor entities, absence of TERT promoter mutations argues for a non-urothelial origin." (PMID 34200508, 2021). "Indeed, we observed significantly smaller tumors whenever telomerase function was lost, indicating a crucial role for TERT in tumor propagation." (PMID 34201898, 2021). "TERT reactivation regenerates telomeres in cells with critically short telomeres sufficiently to maintain them above the critical threshold and to stabilize the tumor genome, thereby maintaining self-renewal potential." (PMID 34944589, 2021). "Indeed, overall, only 3% of all TERT-expressing tumor samples (adult and pediatric) present TERT amplification or translocations." (PMID 33120984, 2020). "A specific region within the THOR, from −668 to −577 bp from the ATG start site (Chr5: 1,295,681–1,295,772), was shown to be hypomethylated in tumor-derived cell lines with TERT promoter mutations compared to those without mutations." (PMID 32121056, 2020). "Recent studies have found that demethylation with 5-aza-2-deoxycytosine could inhibit the expression of TERT gene and telomerase activity, and shorten the telomere length of cancer cells to play a certain anti-tumor effect." (PMID 33041323, 2020). "Regarding tumour size, it was possible to establish opposite behaviours in the benign and malignant tumours, the benign tumours had the highest levels of TERT expression in the smaller tumours, whereas the malignant had the highest levels of expression in the larger tumours." (PMID 32659948, 2020). "Considering that very few single genetic alterations can sufficiently define a tumor type (even 1p/19q codeletion needs to be used in combination with IDH status), TERT promoter mutation may deserve recognition as a diagnostic marker as well." (PMID 33228806, 2020). "This assumption can also explain why the highest levels of TERT expression were found in the smaller tumours; this could represent a diminished ratio of tumour cells/lymphocytes, enhancing the levels of detection of TERT expression." (PMID 32659948, 2020). "In contrast, injection of TERT+/+ ESCs resulted in large tumor masses." (PMID 31911835, 2020). "In multivariate analyses, PLEKHS1 over-expression, age (≥55 years old) and larger tumor size (>4 cm), but not gender and TERT promoter mutations, were independently associated with shorter patient OS." (PMID 32752127, 2020). "Tumour cells overcome telomer shortening by de novo telomer synthesis, which depends upon the maintenance of telomerase expression, activity, and active forms of TERT telomerase reverse transcriptase." (PMID 32536347, 2020). "Mutations in the TERT promoter are thought to be present in nonmalignant urothelium (NMU) during early stages of tumor formation prior to pathological change, but this has not been proven directly." (PMID 32533903, 2020).
tumor (continued). "TERT mRNA expression was detected in both benign and malignant tumours, with increased frequencies in the malignant tumours with aggressive histotypes, larger tumours, and from older patients." (PMID 32659948, 2020). "The expression of the TERT gene has been shown to correlate with telomerase activity in experiments involving NB tumor tissues and to be a prognostic marker in various adult and pediatric tumors, including NB, where high levels of telomerase expression/activity were found to predict poor outcome." (PMID 32825087, 2020). "In addition, our analysis shows that the tumor information measure of correlation is one of the most frequent features in the TERT model as well." (PMID 32111869, 2020). "TERT expression was calculated in paired normal and tumor tissues." (PMID 32932803, 2020). "Moreover, atorvastatin treatment decreased tumor growth and weight in an HCC xenograft animal model, which were associated with decreased IL-6 and TERT expression and STAT3 phosphorylation and increased β-gal expression and SA-β-gal activity in tumors." (PMID 32257389, 2020). "Overexpression of TERT induced by the MAP pathway has shown to aggravate tumor development." (PMID 32324757, 2020). "This links to the phenomenon that some tumor entities lacking specific mutations in the TERT promoter region and where other mechanisms leading to telomerase activation exist." (PMID 32722302, 2020). "Additionally, 18 tumor samples had both ATRX/DAXX truncating or other missense mutations and TERT alterations." (PMID 32024817, 2020). "The BRAF status of the tumor is not correlated to prognosis, whereas the TERT promoter gene mutations are." (PMID 33396957, 2020). "Clinical information for analysis included DE-mRNA signature, age, PFI status, mutational status of BRAF V600E, RAS, RET, NTRK1, and TERT, sex, histological subtype, T stage, N stage, M stage, AJCC stage, residual tumor status, extrathyroidal extension, multifocality, and anatomic site." (PMID 33553144, 2020). "For TERT promoter mutational status, a significant association was observed with histological subtypes (p = 0.03) and with primary tumor localization (p = 0.003), but not with age, sex, Breslow thickness, Clark level, nor AJCC stage." (PMID 32784823, 2020). "In tissue samples, we could show the statistically significant steady increase in TERT methylation levels with increasing tumor grades (p = 0.05, Students t-test; p = 0.003, Spearman correlation)." (PMID 32605217, 2020). "In contrast, Survivin/BIRC5 and TERT genes showed a prominent tumour-enriched expression." (PMID 32152425, 2020). "Although we have not found a positive correlation between presence of TERTp mutations or TERTp methylation levels and mRNA expression values, all tumour cell lines showed TERT expression, supporting that these mechanisms contribute to telomerase-activation in cancer, separate or in combination." (PMID 32267900, 2020). "Since TERT plays a major role in tumor cell immortality through telomere lengthening, this GaDCUS mutation may have revealed a potential driver that contributed to the pathogenesis of this CRC case." (PMID 32188081, 2020). "Telomerase reverse transcriptase (TERT) mutations lead to aberrantly upregulate TERT expression, and ultimately enable telomere maintenance, which achieve unlimited proliferative capacity of tumor cells." (PMID 32915164, 2020). "Multiple genes, such as CDKN2A, DAPK, MGMT, RARB, RASSF1A, and TERT, have been found to be methylated early in lung premalignant lesions, and the level of methylation increases with tumor progression from premalignant lesions to neoplasms." (PMID 32751497, 2020). "On the basis of these 12 features, tumour samples formed 4 distinct subclusters, suggesting that telomere-maintenance mechanisms are more diverse than the well-established TERT and ALT dichotomy." (PMID 32025007, 2020).